RN7SL693P (RNA, 7SL, cytoplasmic 693, pseudogene)
Gene: Miscellaneous RNA gene on chromosome 19 (58,490,797 to 58,491,075, forward strand). Ensembl gene ENSG00000265272.
Homologues: Paralogues in human: RN7SL474P (82% identical), RN7SL811P (82% identical), RN7SL391P (82% identical), RN7SL784P (82% identical), Metazoa_SRP (82% identical), Metazoa_SRP (81% identical), RN7SL774P (81% identical), RN7SL96P (81% identical), RN7SL134P (80% identical), Metazoa_SRP (79% identical), RN7SL163P (79% identical), RN7SL596P (79% identical), and 714 more.